USP47 (ubiquitin specific peptidase 47)
Diseases named in the same sentence as USP47 in open-access papers (continued):
Sharing a sentence is not in itself a finding about the gene and the disease.
tumor (continued). "Targeting USP47 may offer new avenues for developing novel treatments that modulate the immune response and inhibit tumor growth." (PMID 38832955, 2024). "Our study provides valuable insights into the role of USP47 in host anti-tumor immune response." (PMID 38832955, 2024). "Furthermore, we observed significantly lower apoptosis levels of tumor-infiltrating CTLs in Usp47−/− mice compared to wild-type mice." (PMID 38832955, 2024). "Furthermore, using Usp47 knockout mice, we observed a slower tumor growth rate and reduced tumor burden." (PMID 38832955, 2024). "Immunohistochemistry analysis confirmed that the tumor suppressive effect of S.C may indeed rely on activating ROS/USP47/BACH1/HMOX1 axis." (PMID 38195593, 2024). "Together, our findings suggest that miR-101-3p functions as a tumor suppressor by targeting USP47 and could be a potential therapeutic target for cancers." (PMID 35205710, 2022). "Compared with the control group, knockdown of USP47 remarkably reduces the tumor volumes." (PMID 33397955, 2021). "Targeted inhibition of USP47 can reverse malignant tumor behavior." (PMID 34604226, 2021). "Tumor tissues were stained against USP47, Snail, and EMT markers for immunofluorescent analysis." (PMID 29162839, 2017). "To investigate whether the accelerated tumor growth observed in Usp47−/− mice is attributed to changes in the tumor microenvironment (TME), we conducted an analysis of the type and quantity of infiltrating immune cells in tumors derived from Usp47−/− and wild-type mice." (PMID 38832955, 2024). "Notably, the targeted deletion of host Usp47 resulted in an increased percentage of tumor-infiltrating neutrophil granulocytes (CD45+CD11b+Gr-1+), macrophages (CD45+CD11b+F4/80+), natural killer (NK) cells (CD45+NK1.1+), natural killer T (NKT) cells (CD45+NK1.1+CD3+), and T cells (CD45+CD3+)." (PMID 38832955, 2024). "Using the Gene Expression Omnibus (GEO) data sets for COAD, we found that USP47-expressing Tregs from CRC tissues exhibited enrichment with Treg signature genes, indicating that the Treg signature was associated with higher expression levels of USP47 in the tumor-infiltrating Tregs." (PMID 37788092, 2023). "Moreover, endoplasmic reticulum aminopeptidase 1, a key regulator of innate and adaptive anti-tumor immune responses, was found to interact with USP47 and thus interfered with the interaction of USP47 and β-TrCP, leading to ubiquitination degradation of β-TrCP." (PMID 34604226, 2021). "Overexpression of USP47 could reduce the tumor inhibition induced by LINC00668 knockout." (PMID 34604226, 2021). "To explore USP47’s tumor-promoting capacity in vivo, we generated xenograft mouse models by implanting HGC-27 and GT38 cells with USP47 depletion or overexpression into immunodeficient mice." (PMID 39998882, 2025). "Yu et al22 also reported that USP47 and SMURF2 can mediate CC cell proliferation and tumor progression by reversibly manipulating SATB1 ubiquitination." (PMID 37158531, 2023). "In particular, it serves as a tumor suppressor in diverse malignancies by targeting critical oncogenes or anti-oncogenes, including EZH2, DNMT3a, MALAT-1, ZEB1, and USP47." (PMID 35205710, 2022). "The results demonstrated a significant inhibition of RM-1 tumor growth in vivo upon the absence of host Usp47." (PMID 38832955, 2024). "Moreover, we discovered a positive correlation between USP47 expression levels and the infiltration of CD8+ T cells, neutrophils, and macrophages in PRAD, suggesting its potential in regulating the dynamics of tumor cells within the TME." (PMID 38832955, 2024).
tumor (continued). "This suggests that the absence of Usp47 in the host does not significantly affect the overall recruitment of immune cells into the tumor." (PMID 38832955, 2024). "Further, it is conceivable that inhibitors of USP47 and TCEA3 might be effective agents to enhance various chemotherapeutics-induced pyroptosis and increase the effectiveness of anti-tumor therapies." (PMID 34630087, 2021). "USP47 was also found deubiquitinating YAP in the same study, suggesting that the deubiquitinating enzyme may also affect cell growth and tumor initiation under certain circumstances." (PMID 34630087, 2021). "The results of these analyses revealed that the expression level of USP47 in tumor tissues was relatively higher than that in the adjacent normal colon tissues (NC)." (PMID 29162839, 2017). "MiR-204-5p may act as a tumor-suppressor by targeting IL-8, SOX4, USP47 and RAB22A genes and regulating the apoptosis, proliferation, invasion and tumor progression in GC." (PMID 26172537, 2015). "Moreover, immunohistochemical analysis of USP47 protein levels in a tissue microarray composed by 90 CRC samples found higher USP47 expression in tumor tissues, and USP47 expression was positively correlated with tumor size." (PMID 34604226, 2021).
cancer (21 papers, 2017 to 2026). A tumor composed of atypical neoplastic, often pleomorphic cells that invade other tissues. "USP47 has been implicated in several critical cellular processes and identified as a key player in several types of cancers." (PMID 39998882, 2025). "In conclusion, our study identifies a GC-susceptible SNP, rs72856331, located in the promoter region of USP47 and elucidates its causal role in cancer-related phenotypes." (PMID 39998882, 2025). "This elevation in USP47 expression contributes to cancer-related phenotypes through stabilizing Snai1, which in return regulates the EMT signaling pathway." (PMID 39998882, 2025). "The depletion of GLI3 results in a reduction of cancer-related phenotypes, similar to those observed following USP47 knockdown." (PMID 39998882, 2025). "Firstly, we examined the functionality of USP47 in cancer cell proliferation and characterized its biochemical properties." (PMID 37740002, 2023). "A depletion in USP47 decreases cell survival by inducing the accumulation of Cdc25A, and has anti-cancer effects on several cancer cell lines." (PMID 35205710, 2022). "Stabilizing YB-1, a well-known multifunctional transcription factor and an oncoprotein in cancers, also contributes to USP47-mediated IM resistance in CML." (PMID 35091542, 2022). "Here, we show that miR-101-3p enhances the RPL11-induced defense mechanism against abnormal cell proliferation by targeting ubiquitin-specific peptidase 47 (USP47) in cancers." (PMID 35205710, 2022). "Development of targeted inhibitors against USP47 will provide a basis for studying the mechanisms of USP47 and developing therapeutic strategies for cancers and other diseases." (PMID 34604226, 2021). "After introducing the physiological function of USP47 and its role in cancers, we will also introduce the role of USP47 in other diseases." (PMID 34604226, 2021). "The USP47 structure and function data highlight that USP47 is a critical regulator of neurological diseases, cancers, and other diseases." (PMID 34604226, 2021). "This review will provide a basis for studying the mechanisms of USP47 and developing therapeutic strategies for cancers and other diseases." (PMID 34604226, 2021). "USP47 is an active molecule with a wide range of functions and is closely related to cancers and other diseases, including neurological diseases and inflammatory responses." (PMID 34604226, 2021). "While USP47 knockdown sensitized cancer cells to anti-cancer drugs, its enforced expression increased cellular TCEA3 and chemoresistance, which was markedly attenuated by TCEA3 knockdown." (PMID 34630087, 2021). "Next, to determine the role of USP47 in regulating cancer growth in vivo, scrambled siRNA (siControl) and USP47 siRNA were locally administered into A549 xenografts." (PMID 32370049, 2020). "Additionally, USP47 impacts DNA repair mechanisms crucial for maintaining genomic stability and preventing cancer onset." (PMID 38832955, 2024). "USP47 deubiquitinates and stabilizes β-catenin to regulate human cancer cell proliferation." (PMID 37311739, 2023).
cancer (continued). "Therefore, we conducted a comparative analysis to assess the impact of co-depletion of USP7 and USP47 versus individual depletion on cancer cell growth." (PMID 37740002, 2023). "Collectively, these results illustrate the non-redundancy of USP47 compared to USP7 by showing that co-depletion of USP7 and USP47 using siRNA co-transfection results in a more significant reduction of cancer cell growth compared to depleting each independently." (PMID 37740002, 2023). "Moreover, many studies have shown that USP47 exhibits critical functions in cell growth and genome integrity that are closely related to cancer." (PMID 37740002, 2023). "Previous studies have reported that depletion of USP7 or USP47 inhibits cancer cell growth." (PMID 37740002, 2023). "USP4, USP7, and USP47 are DUBs that are abnormally overexpressed in many cancers." (PMID 35884836, 2022). "According to the Protein Atlas database, USP47 is expressed in several cancers." (PMID 34604226, 2021). "Altogether, USP47 is a promising candidate for cancer targeting." (PMID 34604226, 2021). "Ubiquitin-specific peptidase 47 (USP47), a member of the ubiquitin-specific protease family with high homology to USP7, is an active molecule with a wide range of functions and is closely associated with cancer and other diseases." (PMID 34604226, 2021). "Thus far, very little is known about USP47 in cancer, even though USP47 has high sequence similarity with USP7 of whose inhibitors are now actively developed as an anticancer drug." (PMID 32370049, 2020). "Together, these results indicate that the cancer cell phenotype by USP47 depletion was not caused by off-target effects." (PMID 32370049, 2020). "USP47 stabilizes Snail, which promotes cancer progression by blocking TGF-β-induced apoptosis." (PMID 29162839, 2017). "Thus, it is necessary to clarify the mechanisms of the regulation of USP47 expression in cancers." (PMID 34604226, 2021). "Our finding in this study that USP47 is able to deubiquitinate and stabilize TCEA3 indicates that the reduced expression of USP47 may play a significant role in the reduction of TCEA3 in cancers, and it is of great interesting to further identify the E2 and E3 that ubiquitinate TCEA3 in the future." (PMID 34630087, 2021). "Similarly, USP47 might stabilize protein factors involved in DNA double strand break repair, and hence, depletion of USP47 could sensitize cancer cells to the action of DNA damaging agents." (PMID 29786670, 2018). "USP35, USP36, USP37, USP47, USP49, and OTUD6B play crucial roles in cancer progression and chemoresistance across various cancers, including NSCLC." (PMID 41399373, 2026).
cancer (continued). "Specifically, an siRNA knockdown of the deubiquitylating enzyme ubiquitin-specific protease 47 (USP47) reduced POL β protein levels and sensitized cancer cells to MMS and hydrogen peroxide." (PMID 37762489, 2023). "Therefore, USP47 could well be a potential therapeutic target for cancer." (PMID 32370049, 2020). "USP36, USP37, USP47, and OTUD6B exert its oncogenic effects by stabilizing key oncoproteins, such as cellular myelocytomatosis oncogene (c-Myc), 14-3-3γ, Snail, and β-catenin, thereby promoting cancer cell proliferation, migration, and invasion 27-32." (PMID 41399373, 2026). "For example, since 2015, several DUBs-targeted agents, including VLX1570 (targeting USP14), P22077 (targeting USP7/USP10/USP47), P5091 (targeting USP7/USP47), and spautin-1 (targeting USP10/USP13), have been investigated in the clinic to treat certain types of cancers." (PMID 39522000, 2024). "Furthermore, a combination of current chemotherapy regimens together with USP47 inhibition might allow the reduction of the concentration of chemotherapeutic agents without impairing the cytotoxic effect on cancer cells, while reducing side effects." (PMID 29786670, 2018). "The role of PLEKHH2, USP47 and THYN1 has not been extensively studied in cancer progression." (PMID 28122328, 2017).
infection (1 paper, 2023). The state of being infected such as from the introduction of a foreign agent such as serum, vaccine, antigenic substance or organism. "The western blotting analysis of the probe-reacted deubiquitinases was used as a validation, where the level of USP14, USP15, OTUD6B and USP47 was diminished during infection with Y. enterocolitica at 18 hpi." (PMID 37026055, 2023).
neurodegenerative disease (1 paper, 2021). A disorder of the central nervous system characterized by gradual and progressive loss of neural tissue and neurologic function. "According to the effect of USP47 in the regulation of axonal growth in hippocampal neurons, it is meaningful to investigate the role of USP47 in neurodegenerative disease and neurodevelopment." (PMID 34604226, 2021).
USP47 also shares sentences with these, for which no sentence is quoted: acute myeloid leukemia (1 paper); adenocarcinoma (1); brain injury (1); brain tumor (1); cervical cancer (1); diffuse large B-cell lymphoma (1); hematologic malignancies (1); inflammatory bowel disease (1); Liver Fibrosis (1); multiple myeloma (1); neurological diseases (1); stomach cancer (1); vitiligo (1).